RN7SL571P (RNA, 7SL, cytoplasmic 571, pseudogene)
Gene: Miscellaneous RNA gene on chromosome 13 (76,134,931 to 76,135,225, forward strand). Ensembl gene ENSG00000243274.
Homologues: Orthologues: chimpanzee Metazoa_SRP (98% identical). Paralogues in human: RN7SL220P (79% identical), RN7SL1 (79% identical), RN7SL2 (78% identical), RN7SL3 (78% identical), RN7SL566P (78% identical), RN7SL14P (77% identical), RN7SL478P (77% identical), RN7SL336P (76% identical), RN7SL122P (76% identical), RN7SL431P (76% identical), RN7SL481P (76% identical), RN7SL679P (76% identical), and 704 more.